DTYMK (deoxythymidylate kinase)
Diseases named in the same sentence as DTYMK in open-access papers (continued):
Sharing a sentence is not in itself a finding about the gene and the disease.
tumor (continued). "Based on our data, we conclude that DTYMK might regulate the cell cycle to play a crucial role in the development of tumor progression and further lead to poor prognosis." (PMID 36159971, 2022). "Our results confirmed the role of DTYMK in regulating tumor cell migration and clonal formation." (PMID 35903153, 2022). "Furthermore, in an attempt to compare the promoter methylation level of DTYMK between tumor and normal tissues, we performed UALCAN analysis with TCGA samples." (PMID 36159971, 2022). "Moreover, DTYMK is required for DNA double-strand break repair in tumor cells via interactions with ribonucleotide reductase and restriction of dUTP incorporation." (PMID 35903153, 2022). "DTYMK has a potential role in regulating tumor-infiltrating immune cells level and might act as a potential target for immune therapy." (PMID 36159971, 2022). "Taking together, these results indicated that DTYMK might play an important role in tumor progression." (PMID 36159971, 2022). "All of these findings indicated the possibility that DTYMK may promote tumor growth by increasing MSI and TMB via modulating genes implicated in mismatch repair." (PMID 36094557, 2022). "Overexpression of DTYMK can promote tumor cells proliferation and division." (PMID 36159971, 2022). "We next sought to determine what factors were responsible for the endogenous regulation of DTYMK in HCC cells by comparing the expression levels of different miRNAs between tumor and paracancerous tissues in an HCC patient that exhibited robust intratumoral DTYMK expression (Patient 4)." (PMID 35004265, 2021). "Tumor stage and tumor grade were found to be highly correlated with the mRNA expression level of DTYMK in HCC patients, indicating high DTYMK expression probably associated with poor clinical characteristics." (PMID 34049287, 2021). "Besides, the expression of DTYMK was related to tumor stages and grades in HCC according to the results of TCGA." (PMID 34795209, 2021). "However, the role of DTYMK in tumor progression remains to be elucidated." (PMID 36159971, 2022). "Additionally, DTYMK expression correlated with histologic grade, and tumor stage." (PMID 34049287, 2021). "The kinase property of DTYMK has been harnessed for phosphorylating 3′-azido-3′-deoxythymidine (AZT) into AZT-triphosphate (AZT-TP) and disrupting the tumor cell cycle." (PMID 35903153, 2022). "DTYMK promoted the expression of CCL5 by affecting NF-κB, which led to increased infiltration of CD163+ M2-type TAMs in the tumor microenvironment." (PMID 34795209, 2021). "The bioinformatics analysis showed that the expression levels of DTYMK and MAPKAPK2 highly correlated in various tumor types, and they shared the same binding site on miR-378a-3p." (PMID 34795209, 2021). "We found intermediate expression levels of DTYMK and PARP1 in tumor cells." (PMID 39195238, 2024). "According to the results of our validation experiment, the expression level of DTYMK was considerably elevated in LUAD samples as opposed to the matching non-tumor samples." (PMID 36094557, 2022). "Our finding that the mRNA expression of DTYMK is correlated with the T stage, N stage, M stage, and TNM stage in most tumors suggests DTYMK might play a crucial role in the development of tumor progression." (PMID 36159971, 2022). "As miR-148b-3p suppresses the expression of DTYMK in HCC cells, this indicates that this miRNA may function as a tumor suppressor." (PMID 35004265, 2021). "The results show that BIRC5, CENPA, KIF4A, DTYMK, PRC1, and TRIP13 have low beta values in tumor." (PMID 32391055, 2020). "Moreover, DTYMK and PARP1 were also variably expressed in UM tumor cells between patients." (PMID 39195238, 2024). "Importantly, in our 40 pairs of HCC tumor and paracancerous tissues, we detected a negative correlation between miR-148b-3p and DTYMK mRNA expression levels." (PMID 35004265, 2021).
tumor (continued). "In addition, DTYMK could competitively combine with miR-378a-3p to maintain the expression of MAPKAPK2 and thus activate the phospho-HSP27/NF-κB axis, which mediated drug resistance, proliferation of tumor cells, and infiltration of CD163+ M2-type TAMs by inducing the expression of CCL5." (PMID 34795209, 2021).
infection (2 papers, 2015 to 2023). The state of being infected such as from the introduction of a foreign agent such as serum, vaccine, antigenic substance or organism. "Full complementation was observed for the expression levels of TRIM39, SARM1, SLC25A26, NDUFA8 and DTYMK by infection with C∆tbcm, which showed similar trends as wild-type BCG infection." (PMID 38110948, 2023).
neurodegenerative disease (2 papers, 2021 to 2022). A disorder of the central nervous system characterized by gradual and progressive loss of neural tissue and neurologic function. "We report loss-of-function of DTYMK as the genetic cause of a novel, severe neurodegenerative disease in two unrelated individuals with a dramatic neurodevelopmental decline." (PMID 34918187, 2022). "In humans, DTYMK encodesTMPK and recently four DTYMK variants have been identifiedin human patients whosuffered from severe congenital neurodegenerative diseases." (PMID 34926941, 2021). "In summary, by combining genetic and biochemical approaches in multiple models we identified loss-of-function of DTYMK as the cause of a severe postnatal neurodegenerative disease and highlight the essential nature of dTTP synthesis in the maintenance of genome stability and neuronal survival." (PMID 34918187, 2022).
mitochondrial disease (1 paper, 2023). "Furthermore, compared to the wild-type BCG group, the transcriptome of the B∆tbcm group showed downregulated genes, including SLC25A26 (− 3.276-fold), NDUFA8 (− 3.324-fold) and DTYMK (− 2.931-fold); the absence of these genes is associated with mitochondrial disease." (PMID 38110948, 2023).
DTYMK also shares sentences with these, for which no sentence is quoted: tuberculosis (3 papers); clear cell renal cell carcinoma (2); prostate carcinoma (2); systemic lupus erythematosus (2); thyroid cancer (2); acute respiratory distress syndrome (1); adenoma (1); autoimmune disease (1); bladder carcinoma (1); cervical squamous cell carcinoma (1); chronic myeloid leukemia (1); COVID-19 (1); Hashimoto thyroiditis (1); head and neck squamous cell carcinoma (1); hypertrophic cardiomyopathy (1); influenza (1); Intellectual disability (1); kidney chromophobe (1); liver cirrhosis (1); mesothelioma (1); metastatic tumors (1); neurodevelopmental disorder (1); ovarian serous cystadenocarcinoma (1); pancreatic cancer (1); rectum adenocarcinoma (1); sarcoma (1); skin cutaneous melanoma (1); thymoma (1); toxoplasmosis (1); triple-negative breast carcinoma (1).
A further 2 diseases each share a sentence with DTYMK in 1 paper.